FCN1 (ficolin 1)
Diseases named in the same sentence as FCN1 in open-access papers (continued):
Sharing a sentence is not in itself a finding about the gene and the disease.
clear cell renal cell carcinoma (1 paper, 2024). "Paired sample analysis demonstrated low FCN1 expression in multiple tumor samples, such as bladder urothelial carcinoma (BLCA), breast invasive carcinoma (BRCA), and colon adenocarcinoma (COAD), while it exhibited high expression in clear renal cell carcinoma (KIRC)." (PMID 39139822, 2024).
colitis (1 paper, 2023). Inflammation of the colon. "Given that FCN1+ macrophage infiltration was increased in human PIBD mucosa, and FCN1high macrophages had high expression of IL-1β, we then investigated whether there was an association between FCNB (the murine homologue of human FCN1) and IL-1β in the mouse model of colitis." (PMID 36932401, 2023). "Therefore, we further determined involvement of FCN1 in PIBD using DSS-induced murine colitis model." (PMID 36932401, 2023). "The expression of FCN1 was significantly increased in both colorectal biopsies and blood of PIBD compared to non-IBD in both public bulk transcriptomic datasets and our clinical cohort, which was further validated in the mouse model of DSS-induced colitis." (PMID 36932401, 2023).
colon cancer (1 paper, 2022). "In human colon cancer, FCN1+ monocytes enriched in tumors show a similar pattern to blood CD14+ monocytes, probably migrating to tumors and obtaining some tumor-specific transcriptional profiles." (PMID 35646915, 2022). "According to a human single-cell colon cancer dataset, C1QC+ and SPP1+ TAMs are likely to differentiate from FCN1+ monocytes in tumors." (PMID 35646915, 2022).
gastric cancer (1 paper, 2022). A primary or metastatic malignant neoplasm involving the stomach. "These molecular characteristics were mainly driven by the eight NRGPI oncogenes (CYTL1, PLCL1, CNTN1, GRP, APOD, GPX3, FCN1, SERPINE1) as validated in the gastric cancer cell lines and clinical samples." (PMID 36389725, 2022).
graft versus host disease (1 paper, 2025). An immune system disorder that occurs after allogeneic hematopoietic stem cell transplant and is a reaction of donor immune cells against host tissues. "Multiplex immunohistochemistry revealed increased numbers of S1PR2+CD45+CD68+FCN1+ inflammatory macrophages and S1PR2+CD45+CD68+MARCO+ Kupffer cells in liver tissues showing ductopenia due to graft-versus-host disease and rejection post-liver transplant compared with normal liver." (PMID 39854311, 2025).
hepatocellular carcinoma (1 paper, 2022). A malignant tumor that arises from hepatocytes. "ROC analysis was applied to evaluate the effectiveness of FCNs mRNA expression levels in distinguishing hepatocellular carcinoma from normal liver tissue, and the AUC of FCN1 was 0.697 (95% CI: 0.628-0.767) obtained by analysis of TCGA-LIHC data." (PMID 35928441, 2022).
hyperlipidemia (1 paper, 2019). "Subsequent analysis of the diagnostic value of these genes in obstructive CAD further confirmed that NCF2, MYO1F, S1PR4, and FCN1 together with risk factors, gender, and hyperlipidemia, could improve the diagnostic accuracy of distinguishing obstructive CAD from free of obstructive CAD." (PMID 31245869, 2019). "All these data demonstrate that NCF2, MYO1F, S1PR4, and FCN1 in PBMC combination with sex and hyperlipidemia could be diagnostic biomarkers for obstructive CAD." (PMID 31245869, 2019).
kidney failure (1 paper, 2025). An acute or chronic condition that is characterized by the inability of the kidneys to adequately filter the blood. "In that study, high FCN1 levels predicted development of kidney failure, defined as recorded initiation of KRT in the Danish Renal Registry, but FCN2 did not." (PMID 40342947, 2025).
lepromatous leprosy (1 paper, 2020). A chronic communicable infection which is a principal or polar form of leprosy. "Nevertheless, some associations were lost after multivariate logistic correction (FCN1*3C2, FCN2*AGAAGC, and FCN2*GGGCAC with lepromatous leprosy/HBV infection and MBL2*HYPA, MBL2*LYQC, FCN2*GGGCAC with non-lepromatous leprosy/HBV infection) or due to low sample size (MASP1*AC_CTG, FCN3*2B2.2A)." (PMID 33643280, 2020).
leukocytosis (1 paper, 2020). "Interestingly, although ficolin-1 levels correlated with white blood cell (WBC) and more weakly with platelet (PLT) counts (r = 0.49, p < 0.000001 and r = 0.24, p = 0.003, respectively), high leukocytosis was often associated with low ficolin-1." (PMID 32601370, 2020).
liver cancer (1 paper, 2024). An epithelial or non-epithelial malignant neoplasm that arises from the liver. "Studies from liver cancer also highlighted the significant association between FCN1 and its immune response and apoptosis." (PMID 39139822, 2024).
Lung Squamous Cell Carcinoma (1 paper, 2024). "HRD status, a critical indicator for treatment selection and prognosis in various tumors, demonstrates significant positive correlations with FCN1 in Basal-like BRCA and OV, while displaying negative associations with Mesothelioma (MESO) and Lung Squamous Cell Carcinoma (LUSC)." (PMID 39139822, 2024).
melanoma (1 paper, 2024). A malignant, usually aggressive tumor composed of atypical, neoplastic melanocytes. "Survival analysis underscored a significant association between high FCN1 expression and prolonged OS in PD1-treated ccRCC and CTLA4-treated melanoma cohorts." (PMID 39139822, 2024). "Moreover, a higher proportion of patients in the FCN1 high expression group within the melanoma dataset PRJEB23709 demonstrated responsiveness to immunotherapy." (PMID 39139822, 2024). "Notably, FCN1 exhibited variable prediction performance across datasets, with superior performance observed in the melanoma dataset PRJEB23709 (AUC: 0.737; 95%CI: 0.631–0.837)." (PMID 39139822, 2024).
Parkinson disease (1 paper, 2022). A progressive degenerative disorder of the central nervous system characterized by loss of dopamine producing neurons in the substantia nigra and the presence of Lewy bodies in the substantia nigra and locus coeruleus. "We noted that the significant enrichment of inhibited terms comprised ficolin-1-rich granule, mitochondrial inner membrane and ribosome in gene ontology cellular component (GO_CC) and Parkinson disease, cell cycle and salvage pyrimidine ribonucleotides in Panther pathway." (PMID 36362897, 2022).
Pheochromocytoma and Paraganglioma (1 paper, 2024). "Through univariate Cox and log-rank test analyses, we discerned that FCN1 exhibited prognostic significance across a spectrum of cancers, excluding BRCA, KICH, KIRP, Pheochromocytoma and Paraganglioma (PCPG), Rectum adenocarcinoma (READ), Thyroid carcinoma (THCA), and UCEC." (PMID 39139822, 2024).
serous cystadenoma (1 paper, 2019). A serous neoplasm in which the cysts and papillae are lined by a single layer of cells without atypia, architectural complexity or invasion. "Both ARX and FCN1 had a very low level of expression in samples of FTE, OEI, serous cystadenoma, SBT, and LGSC, but highly expressed in OSEs." (PMID 30949203, 2019).
Skin Cutaneous Melanoma (1 paper, 2024). "The mutation rate of FCN1 varies across different cancer types, with notably higher rates observed in UCEC and Skin Cutaneous Melanoma (SKCM)." (PMID 39139822, 2024).
transient ischemic attack (1 paper, 2017). A brief attack (from a few minutes to an hour) of cerebral dysfunction of vascular origin, with no persistent neurological deficit. "Symptomatic patients experiencing a transient ischemic attack had lower plasma levels of ficolin-1." (PMID 28360913, 2017). "Our data originally show ficolin-1 presence within atherosclerotic plaques and its significantly lower levels in symptomatic patients with transient ischemic attacks compared to non-symptomatic." (PMID 28360913, 2017).
viral infections (1 paper, 2018). "Studies relating the role of Ficolin-1 and -3 in viral infections are scarce and to our knowledge, this is the first study evaluating the levels of Ficolin-1 and -3 in HIV and HIV/HCV coinfected patients." (PMID 30349535, 2018). "We provide here the first assessment of Ficolin-1 and−3 levels in HIV and HIV/HCV coinfected patients, which indicates a distinct role for these pattern recognition molecules in both viral infections." (PMID 30349535, 2018).
tumor (36 papers, 2020 to 2026). "Tumour-associated macrophages (TAMs) originate from both FCN1+ monocytes and FOLR2+ tissue-resident macrophages, displaying two polarisation states with distinct prognostic associations." (PMID 41636115, 2026). "CD14-positive cells localized to clusters 0, 3, 5, 6, and 14 and were classified as mutually exclusive TREM2 and FCN1 tumor-associated macrophages (TAMs), as previously reported." (PMID 41228323, 2025). "FCN1+ TAMs are thought to represent an intermediate stage in the maturation of monocytes into tumor macrophages and are associated with angiogenesis." (PMID 40034694, 2025). "To validate the transcriptional data, we performed immunofluorescence microscopy on multiple advanced-stage MF samples staining for FPR2 and FCN1 to identify MF-specific tumor-associated macrophages (TAMs) and CLEC4C and LILRA4 to identify pDCs." (PMID 37669110, 2023). "Cellular component enrichment analysis indicated that the tumor genes were closely associated with the CC terms including tertiary granule, secretory granule membrane, and ficolin-1-rich granule." (PMID 36284631, 2022). "By analyzing the correlation of FCNs expression with tumor mutation burden and microsatellite instability in 33 type of human tumors, FCN1 expression was found to be significantly correlated with MSI of HCC (p < 0.05); FCN3 expression was significantly correlated with TMB and MSI of HCC (p < 0.05)." (PMID 35928441, 2022). "In the anti-tumor M2 module, cDC2 was positioned at the most upstream level, capable of activating Macro_INHBA, Mono_FCN1, and various T cells, while CD8_Teff and Trm were downstream recipients of regulatory signals." (PMID 40740771, 2025). "The metastatic TME schematic depicts the coexistence of immunosuppressive (SPP1+ TAMs) and inflammatory (FCN1+ TAMs) macrophage subsets within spatially distinct tumor regions." (PMID 40458409, 2025). "Immunological investigations elucidate FCN1’s involvement in modulating inflammatory responses within the tumor microenvironment and its correlation with treatment efficacy." (PMID 39139822, 2024). "Assessment of FCN1 expression across 33 tumor datasets from TCGA revealed dysregulated expression in over one-third of tumor types compared to normal tissue." (PMID 39139822, 2024). "By elucidating FCN1’s role in tumor immunology, our research aims to provide insights into its potential mechanisms and offer avenues for clinical diagnosis and immunotherapeutic exploration." (PMID 39139822, 2024). "FCN1 likely participates in regulating the tumor microenvironment, influencing tumor initiation and progression." (PMID 39139822, 2024). "We investigated the correlation between effector genes of tumor-associated immune cells (CD8 T-cell, NK cell, macrophage, Th1 cell, Dendritic cell) and FCN1 expression." (PMID 39139822, 2024). "FCN1’s impact on tumor development likely involves its regulatory influence on tumor-associated inflammatory responses." (PMID 39139822, 2024). "The FCN1+ Mac subpopulation was significantly less abundant in tumor cells than in adjacent controls." (PMID 37333982, 2023). "Among them, the APOC1+ Mac subpopulation was a major component of HCC macrophage ecology compared to levels in adjacent control tissue, whereas the abundance of the FCN1+ Mac subpopulation was significantly decreased in tumor cells." (PMID 37333982, 2023). "FCN1(+) TAMs are considered as an intermediate stage during monocyte maturation into tumor macrophages." (PMID 35784460, 2022). "In the tumor microenvironment (TME), macrophages are divided into two main subsets: C1Q+ and SPP1+ tumor-associated macrophages (TAMs), as well as two secondary subsets: FCN1+ and CCL18+ TAMs." (PMID 40034694, 2025). "FCN1 expression positively correlates with various immune regulatory factors, including immunosuppressive factors and chemokines, suggesting its ability to modulate immune system function, thereby impacting tumor onset and treatment efficacy." (PMID 39139822, 2024).
tumor (continued). "Interestingly, the proportion of the Mac_MEG3 cluster in tumour samples was found significantly increased, while Mac_FCN1 and Mac_CCL3 clusters were significantly dominant in normal samples." (PMID 39548559, 2024). "Enriched FCN1+ TAMs were detected in tumor-adjacent tissues." (PMID 38347955, 2023). "These FCN1+ TAMs were considered an intermediate stage from monocytes to tumor macrophages." (PMID 38347955, 2023). "Indeed, tumor-enriched FCN1+ monocyte-like cells showed a high similarity to blood CD14+ monocytes, representing a monocyte population migrating into tumors and harboring a tumor-specific transcriptional program." (PMID 38347955, 2023). "The residual tumor contained 98.0% (1,288 cells) C3 TAMs, which expressed FCN1." (PMID 35784460, 2022). "In contrast to tumor-preferred C1Q (+) TAMs, FCN1 (+) TAMs are enriched in tumor-adjacent tissue." (PMID 35784460, 2022). "Notably, FCN1 expression demonstrates dysregulation across most tumor types, particularly in AML." (PMID 39139822, 2024). "Notably, the FCN1 low expression group exhibited a higher tumor stemness score." (PMID 39139822, 2024). "Notably, FCN1 exhibited a significant positive correlation with monocyte and macrophage infiltration, indicative of its crucial role in modulating the immune response in tumor patients and shaping the tumor microenvironment." (PMID 39139822, 2024). "Compared to normal tissues, the tumor group exhibited a higher abundance of Macro-FOLR2, Macro-SPP1 and cDC-FCER1A, with a lower proportion of Mono-FCN1." (PMID 39093451, 2024). "Discrepancies between FCN1 mRNA and protein expression in COAD, OV, suggest a potential mediation by methylation alterations, known to play pivotal roles in tumor initiation and progression." (PMID 39139822, 2024). "We also demonstrate that RCT elicits anti-tumor immune responses, including the recruitment of CD16+ NK cells with higher cytotoxic gene expression and FCN1+ M-MDSC cells with increased pro-inflammatory features." (PMID 36710358, 2023). "Among the identified five distinct macrophage subpopulations (FCN1+Inflam-Mac, PRDX1+LA-Mac, HERPUD1+LA-Mac, ALOX5AP+LA-Mac and OxP-Mac), OxP-Mac predominantly enriched in normal kidney tissues, whereas the other subtypes were mainly found in tumor regions." (PMID 41601657, 2026). "Genomic heterogeneity analysis reveals significant positive correlations between FCN1 and MSI and Mutant-Allele Tumor Heterogeneity (MATH) in AML, contrasting with negative correlations observed in TGCT." (PMID 39139822, 2024). "Upregulation of FCN1 potentially enhances immune cell activation (e.g., CD4 T cells, CD8 T cells, NK cells, Th1 cells, and MDSC) and their infiltration into tumors by modulating the expression of chemokines, their receptors, and cell adhesion molecules in the tumor microenvironment." (PMID 39139822, 2024). "Our findings unveiled a notable negative correlation between FCN1 expression and the stemness score in AML, indicating that tumor cells with reduced FCN1 expression harbor heightened stemness and may develop resistance to treatment." (PMID 39139822, 2024).
infection (21 papers, 2009 to 2025). The state of being infected such as from the introduction of a foreign agent such as serum, vaccine, antigenic substance or organism. "Moreover, the low pH of infection conditions can cause a significant interaction between ficolin-1 and CRP." (PMID 36825008, 2023). "Another possible explanation for the observed preferential binding of ficolin-1 to the iRBCs is that there was preferential infection of younger RBCs by the parasite." (PMID 40422078, 2025). "Additionally, the FCN1 protein plays a crucial role during infection and inflammation, facilitating pathogen clearance, including bacteria, fungi, and viruses, by recognizing and binding to their surface carbohydrate structures." (PMID 39139822, 2024). "FCN1 may also interact with C-reactive protein (CRP) via a conformational change induced by mild acidosis at the local site of infection, and with pentraxin 3 (PTX3) in a Ca2+-dependent manner." (PMID 31694344, 2019). "The authors suggested that Ficolin-1 may be downregulated by the isu domain of gp41 thereby preventing early local innate response, allowing infection and virus replication." (PMID 30349535, 2018). "Concluding, we suggest a role for ficolin-1 in fighting GAS infection, with a possible damaging effect when infection succeeds, due to excessive complement activation." (PMID 30619357, 2018). "In fact, there was a decrease in the mRNA levels of innate-immunity related genes from blood mononuclear cells following intramammary infection with M. bovis, such as complement factor D (CFD), ficolin 1 (FCN1), and tumor necrosis factor superfamily member 13 (TNFSF13)." (PMID 38515536, 2024). "Rather, genes involved in host defense, such as FCN1 and TYROBP expressed in EBOV-Mayinga infection, and numerous protein chaperones highly upregulated in EBOV-Makona C07 infection, were sufficient to separate infections." (PMID 34484156, 2021). "First of all, down-regulation of FCN1, CXCL9 and SEPP1 may prevent early local innate immune responses against the virus allowing infection and replication." (PMID 23383108, 2013).